CD34 (CD34 molecule)
Diseases named in the same sentence as CD34 in open-access papers (continued):
Sharing a sentence is not in itself a finding about the gene and the disease.
diabetic nephropathy (2 papers, 2024 to 2025). "Human cultured CD34+ cells improved urinary protein excretion and pathological damage in rats with diabetic nephropathy." (PMID 41294818, 2025). "Given the clinical need for effective therapies, we examined the potential of CD34+ cell therapy in an animal model of diabetic nephropathy." (PMID 41294818, 2025). "Human cultured CD34+ cells acted against the injury of diabetic nephropathy in spite of a high blood glucose environment." (PMID 41294818, 2025). "The results of this study support the validity of future clinical trials using CD34+ cells to treat diabetic nephropathy." (PMID 41294818, 2025). "In rats with STZ-induced diabetic nephropathy, human CD34+ cells ameliorated renal injury through their anti-inflammatory and pro-angiogenic effects." (PMID 41294818, 2025). "Observational studies have previously found a significant reduction in the number of CD34+ HSC in diabetic nephropathy, with the microalbumin/creatinine ratio of patients moderately negatively correlated with the number of these cells." (PMID 39014501, 2024). "Although a lack of enough evaluation about several basic mechanisms of diabetic nephropathy, human CD34+ cells could protect against the progression of diabetic nephropathy via angiogenesis and anti-inflammatory related mechanisms." (PMID 41294818, 2025). "Human CD34+ cells have a regenerative effect and the potential to improve diabetic nephropathy." (PMID 41294818, 2025). "Accordingly, we hypothesized that the robust angiogenic and anti-inflammatory potential of CD34+ cells could be effective in treating diabetic nephropathy." (PMID 41294818, 2025). "Confirming the efficacy and mechanisms of CD34+ cells in animal models could pave the way for translational trials in patients with diabetic nephropathy." (PMID 41294818, 2025). "We just focused on evaluating whether the strong angiogenic/vasculoprotective and anti-inflammatory potential that CD34+ cells possess may alter and improve the progression of diabetic nephropathy." (PMID 41294818, 2025). "However, we wanted to know the effect of human CD34+ cells on pre-established overt diabetic nephropathy, in consideration of a future clinical trial for overt diabetic nephropathy in humans." (PMID 41294818, 2025). "This study examined the efficacy of human CD34+ cells against diabetic nephropathy in rats." (PMID 41294818, 2025). "We speculate that the increase in CD34 on Hematopoietic Stem Cells may be related to the development of subsequent diseases in diabetic nephropathy, warranting further exploration." (PMID 39014501, 2024). "To conclude, cultured human CD34+ cells markedly improved urinary albumin excretion and attenuated pathological damage in a rat model of STZ-induced diabetic nephropathy, in spite of a hyperglycemic environment, highlighting their angiogenic and anti-inflammatory potential." (PMID 41294818, 2025). "Although a few preclinical studies have reported the efficacy of CD34+ cells for diabetic nephropathy, clinical trials are currently lacking." (PMID 41294818, 2025). "In consideration of the chronic and progressive nature of diabetic nephropathy and the purpose of future clinical application, we selected repetitive administration of human CD34+ cells, not a single injection, for diabetic nephropathy." (PMID 41294818, 2025). "First, we did not perform CD34+ cell administration at an earlier phase in STZ-induced diabetic nephropathy." (PMID 41294818, 2025). "To date, no clinical trial has investigated the potential of CD34+ cells to treat diabetic nephropathy." (PMID 41294818, 2025). "Therefore, the efficacy of early intervention using CD34+ cells on the onset of diabetic nephropathy could not be elucidated." (PMID 41294818, 2025).
DiGeorge Syndrome (2 papers, 2021 to 2022). "CD34 is furthermore intracellularly coupled to CRKL, which has been associated with congenital kidney anomalies in DiGeorge Syndrome, including microcystic tubules and glomeruli." (PMID 34301992, 2021).
eczema (2 papers, 2023 to 2025). "Previous reports showed that blood CD34+ could promote allergic inflammation and eczema is an inflammatory disease." (PMID 37836533, 2023).
End Stage Liver Disease (2 papers, 2014 to 2023). Final stage of a liver disease when the liver failure is irreversible and LIVER TRANSPLANTATION is needed. "We previously showed that a CD34+ and CD133+ stem cells infusion can be used as supportive treatment for end-stage liver disease in the Egyptian population with satisfactory tolerability." (PMID 24886681, 2014). "In the current study, we sought to assess the possibility of using MSCs followed by G-CSF mobilization intravenous infusion as a therapeutic modality in patients with end-stage liver diseases in comparison to our previous studies using CD133 and CD34 intrahepatic infusion." (PMID 24886681, 2014).
epithelioid hemangioma (2 papers, 2008 to 2011). A hemangioma characterized by the presence of epithelioid endothelial cells. "After surgical resection, histopathological examination of the resected specimen confirmed the diagnosis of epithelioid hemangioma of the colon, which was backed up by the immunohistochemical panel (factor VIII, Ki-67, CD-34)." (PMID 19099166, 2008). "On immunohistochemical staining, epithelioid hemangiomas are positive for CD31, CD34 and factor VIII-related antigen and negative for keratin and epithelial membrane antigens." (PMID 21718503, 2011).
erythrocytosis (2 papers, 2014 to 2015). "Two features helped confirm that the reactive polycythemia was secondary to this tumour, namely, normalisation of polycythemia postoperatively and positive CD34 tumour staining, which is a marker of early haematopoietic cell line activity." (PMID 25431722, 2014).
esophageal adenocarcinoma (2 papers, 2012 to 2020). A malignant tumor with glandular differentiation arising predominantly from Barrett mucosa in the lower third of the esophagus. "In this study, a high proliferation index in oesophageal adenocarcinoma was associated with poor outcome (on univariate survival analysis) and was also associated with intra-tumoural macrophage infiltration (CD68+) and microvessel density (CD34+)." (PMID 22240784, 2012).
fibromyxoid tumor (2 papers, 2020 to 2024). A soft tissue tumor of uncertain lineage characterized by the presence of neoplastic spindle-shaped to round cells in a fibromyxoid stroma. "Ossifying fibromyxoid tumors frequently exhibit capsular ossification and are negative for CD34." (PMID 39202049, 2024).
fungal infections (2 papers, 2022 to 2024). "Several studies have observed that a higher CD34+ cell dose in harvests could improve neutrophil and platelet engraftment, induce faster monocyte and lymphocyte recovery, and decrease the incidence of fungal infections." (PMID 35392613, 2022).
gallbladder cancer (2 papers, 2025). "For instance, in gallbladder cancer, the CD34+CD90+ endothelial cell subset undergoes endothelial-to-mesenchymal transition (EndoMT) via activation of the TGF-β signaling pathway, acquiring stromal-like properties that enhance its capacity to promote tumor invasion and metastasis." (PMID 41303611, 2025). "This study isolated endothelial cells from gallbladder cancer (GBC) and identified the SAEndo2 (CD34+CD90+ EC) subset." (PMID 41154806, 2025).
granuloma annulare (2 papers, 2020 to 2021). Granuloma annulare is a long-term (chronic) skin disease consisting of a rash with reddish bumps arranged in a circle or ring. "Granuloma annulare, which shows degenerated collagen, variable mucin deposition, loss of elastic component and a palisading or interstitial inflammatory infiltrate (palisading and interstitial variants), is a good example of the CD34+SC/TC response in skin granulomatous lesions." (PMID 34298962, 2021).
heart tumors (2 papers, 2015 to 2023). "Immunohistochemical analysis with antibodies against CD34 and CD68 was also conducted on the same 11 Post-COVID period heart tumors." (PMID 37895467, 2023).
Hepatitis (2 papers, 2018 to 2025). Inflammation of the liver. "The level of circulating CD34+ cells in peripheral blood of CHB patients paralleled with the hepatitis B viral load." (PMID 29461203, 2018).
hereditary retinal degeneration (2 papers, 2016 to 2025). "In this study, we used a murine model of hereditary retinal degeneration (rd1) to study the effect of human BM CD34+ stem cells on the degenerating retina following intravitreal administration." (PMID 27537262, 2016).
Impaired glucose tolerance (2 papers, 2016 to 2022). An abnormal resistance to glucose, i.e., a reduction in the ability to maintain glucose levels in the blood stream within normal limits following oral or intravenous administration of glucose. "The reduction of the circulating CD34+ progenitor cells in early stages of T2DM can be suggested in individuals with impaired glucose tolerance; this reduction persists over time and worsens in patients with advanced complications." (PMID 26839569, 2016). "From the trials that incorporated a MICON protocol, one trial reported a 23% increase on CD34+/KDR+ EPCs in a normal glucose tolerance group, while no changes were observed in the impaired glucose tolerance and T2DM groups." (PMID 35022875, 2022).
influenza infection (2 papers, 2016 to 2020). "Evaluation of localization of CD31+ and CD34+ cells in control and damaged lungs by IHC revealed striking differences after influenza infection." (PMID 32091393, 2020). "BLVRB, biliverdin reductase B, is according to FANTOM5 expressed in CD34 + cells, as well as in whole blood and in monocyte-derived macrophages responding to certain influenza infections and in bronchial epithelial cells." (PMID 27632927, 2016). "In alveolar space adjacent to the regions of diffuse alveolar damage after influenza infection, a dramatic increase in CD34 protein suggests that these cells may participate in repair and regeneration of damaged alveoli." (PMID 32091393, 2020). "Taken together, these data indicate that damage to the alveolar space through either influenza infection or bleomycin injury results in increased CD34+ cells in areas adjacent to the greatest tissue damage, suggesting that these cells may play a role in regeneration of injured alveoli." (PMID 32091393, 2020).
interstitial lung disease (2 papers, 2016 to 2019). A diverse group of lung diseases that affect the lung parenchyma. "CD14+, CD34+, and Col I+ spindle-shaped cells have been found in increased numbers in lungs of SSc patients with interstitial lung disease." (PMID 27158466, 2016).
intestinal polyp (2 papers, 2012 to 2017). Discrete abnormal tissue masses that protrude into the lumen of the intestine. "Notably, the endothelial marker CD34 (a marker of endothelial vasculature), was significantly lower in the stromal tissue of intestinal polyps from Slco2a1-deficient ApcΔ716/+ mice." (PMID 29185482, 2017). "The extent of the CD34-positive area was compared in intestinal polyps between the Slco2a1+/+/Apc∆716/+ and Slco2a1−/−/ApcΔ716/+ mice." (PMID 29185482, 2017). "We first examined the microvessel density (MVD) in intestinal polyps of 2–3 mm size by CD34 immunohistochemical staining assay." (PMID 22432006, 2012).
intimal sarcoma (2 papers, 2015 to 2019). A malignant neoplasm arising from the large blood vessels. "Despite not displaying reactivity for other endothelial markers, CD31 and CD34, the tumor was classified as an undifferentiated intimal sarcoma." (PMID 26106489, 2015). "Vimentin is frequently positive in intimal sarcoma, whereas vascular markers such as CD31, CD34, vWF, and smooth muscle cell markers such as desmin are usually negative." (PMID 30925179, 2019).
Lipedema (2 papers, 2022). Disorder of adipose tissue characterized by symmetric and bilateral enlargement of the lower extremities due to abnormal deposition of subcutaneous fat often in obese women. "The higher proliferation rate of lipedema ADSCs (lipedema AT had a higher number of precursor cells identified by CD29+/CD34+ expression) was linked to an increased expression level of genes involved in cell-cycle regulation and proliferation." (PMID 36551837, 2022). "Next, we quantified the numbers of CD29+/CD34+ cells in tissue specimens and found that lipedema adipose tissue showed greater numbers of CD29+/CD34+ ADSCs compared to control tissue, suggesting a greater propensity to generate fat when stimulated." (PMID 34764426, 2022). "Having demonstrated key differences in lipedema tissues, including higher numbers of CD29+/CD34+ ADSCs, we next focused on the role of these ADSCs, as stem cells play key roles in many diseases, and ADSCs are precursors to adipocytes that may underpin the pathogenesis of lipedema." (PMID 34764426, 2022).
lipoblastoma (2 papers, 2025). A lipoma usually occurring in the extremities of young children (usually boys). "Lipoblastomas typically occur in infants and children, and even in older children and adult patients, positivity for PLAG1, CD34, and desmin, along with PLAG1 and HMGA2 rearrangements, aids in diagnosis." (PMID 41230282, 2025). "An initial excisional biopsy confirmed a lipoblastoma-like tumor, characterized by spindle cells in a myxoid stroma, focal positivity for CD34 and S100, and absence of DDIT3 rearrangement." (PMID 41246635, 2025). "Lipoblastoma typically occurs in infants and children and often shows pleomorphic adenoma gene 1 (PLAG1) overexpression and PLAG1/HMGA2 rearrangements, with frequent cluster of differentiation 34 (CD34) and desmin expression." (PMID 41230282, 2025).
metastatic melanoma (2 papers, 2020 to 2023). A melanoma that has spread from its primary site to another anatomic site. "The use of CD34-derived DCs for vaccination has been limited to an autologous DC vaccination setting for the treatment of metastatic melanoma." (PMID 33101274, 2020).
monoclonal gammopathies (2 papers, 2015 to 2019). "Under physiological conditions, long-living BM PCs are not driven to circulate in PB; conversely, CTCs are increased in monoclonal gammopathies, following a circadian rhythm similar to CD34+ cells." (PMID 31482061, 2019). "Thus we were interested in verifying the distribution of BM CD34+ HPCs in healthy controls, and monoclonal gammopathy of undetermined significance (MGUS) patients and various categories of responding/relapsing MM subjects divided according to CD117 positivity." (PMID 26101540, 2015).
mucopolysaccharidosis type 1 (2 papers, 2019 to 2022). The most common type of mucopolysaccharidosis. "Clinical trials with gene therapy are conducted in patients with mucopolysaccharidosis type I. However, they are based on viral vectors or autologous transplantation of modified CD34+ hematopoietic stem cells." (PMID 35563175, 2022).
muscular dystrophy (2 papers, 2013 to 2022). Muscular dystrophy (MD) refers to a group of more than 30 genetic diseases characterized by progressive weakness and degeneration of the skeletal muscles that control movement. "Interestingly, the expression of the myogenic markers cadherin-13 (CDH13) and CD34 were both elevated in muscular dystrophy." (PMID 36362832, 2022).
neuroendocrine carcinoma (2 papers, 2020 to 2024). A malignant neuroendocrine neoplasm composed of cells containing secretory granules that stain positive for NSE and chromogranin. "(bladder) combined with immunohistochemical staining supports high-grade neuroendocrine carcinoma, considered to be a large cell neuroendocrine carcinoma, invading the muscle proper of the bladder wall, showing intravascular cancer embolus(CD31,CD34,D2-40) and nerve infiltration." (PMID 39156709, 2024).
oral cancer (2 papers, 2024 to 2025). "Biomarkers such as l‐phenylalanine, CD34, and integrins can aid in the timely diagnosis and monitoring of oral cancer." (PMID 41017868, 2025). "CD31, a protein expressed on the surface of endothelial cells, is widely used as a prognostic marker of vascular density in malignant tissue, including oral cancer as well as CD34, an important cell adhesion factor." (PMID 39204206, 2024).
osteopetrosis (2 papers, 2020 to 2021). Osteopetrosis, also known as marble bone disease, is a descriptive term that refers to a group of rare, heritable disorders of the skeleton characterized by increased bone density on radiographs. "In our previous studies, we have provided proof of concept for an autologous approach to treating osteopetrosis by hematopoietic stem cell-targeted gene therapy with clinically applicable lentiviral vectors in IMO patient CD34+ peripheral blood cells and in the oc/oc osteopetrotic mouse model." (PMID 32414402, 2020).
placental insufficiency (2 papers, 2021 to 2023). Failure of the placenta to deliver an adequate supply of nutrients and oxygen to the fetus. "In preterm infants with placental insufficiency, umbilical cord milking was associated with greater peripheral blood CD34 percentage, hemoglobin levels initially and at postnatal age of 2 months, alongside significantly shorter duration of oxygen therapy compared with ICC group." (PMID 35310142, 2021). "Our results are like another recent study from our center that concluded that DCC led to higher CD34+ stem cells transfusion in PT babies with placental insufficiency." (PMID 38129640, 2023). "UCM in preterm neonates born to mothers with placental insufficiency was feasible and resulted in greater CD34 percentage, higher initial hemoglobin level, higher peak serum bilirubin, significant increase of phototherapy initiation, and higher hemoglobin level at 2 months." (PMID 35310142, 2021). "Yet, neonates with placental insufficiency who underwent UCM still had significantly lower CD34 percentage compared to those in No PI+UCM group [median (IQR) of 1.05 (0.70–1.50) vs. 2.40 (1.80–2.80), p < 0.0001]." (PMID 35310142, 2021).
pressure ulcers (2 papers, 2023 to 2024). "We examined CD45−/CD31−/CD34+ preadipocytes and CD68+ macrophages in human granulation tissue from pressure ulcers (n=6) using immunofluorescence, immunohistochemistry, and flow cytometry." (PMID 37904253, 2023).
prostate adenocarcinoma (2 papers, 2022 to 2025). "Angiogenesis represents a prognostic factor by using CD34 as an endothelial biomarker in various solid tumors, including prostate adenocarcinoma." (PMID 35884977, 2022).
renal dysfunction (2 papers, 2018 to 2025). "For NSF, diagnosis combines characteristic clinical signs (skin thickening, contractures) with histopathology (increased dermal cells, CD34 + fibrocytes, collagen) within the context of GBCA exposure and renal dysfunction." (PMID 40608128, 2025).
renal tumors (2 papers, 2013 to 2024). "Increased levels of Glut1 and IGF1R expression, high Ki67 labeling index, and a dense network of CD34+ microvessels in renal tumors was consistent with increased 18F-FDG accumulation." (PMID 22875335, 2013). "This case emphasizes the need to consider SFT in the differential diagnosis of unusual renal tumors, even when CD34 is negative." (PMID 39006570, 2024).
retinal ischemia (2 papers, 2014 to 2020). A ischemic disease that involves the retina. "Previously, we have shown that the diabetic cells do not respond to hypoxia in in vivo models of retinal ischemia and we have also demonstrated that the diabetic CD34+cells do not migrate towards hypoxia regulated factors, SDF-1 and VEGF." (PMID 24713821, 2014).
retinoblastoma (2 papers, 2022 to 2024). A malignant tumor that originates in the nuclear layer of the retina. "In addition, immunohistochemistry (IHC) showed positive staining for CD34 and heterogeneous retinoblastoma deficiency, and fluorescence in situ hybridization (FISH) showed no amplification of mouse double minute 2 homolog and no rearrangement of FUS or EWSR1." (PMID 36439417, 2022). "Immunohistochemical expression of CD34 and desmin is commonly detected, whereas retinoblastoma gene (Rb) expression is absent." (PMID 39345656, 2024).